IL15 (interleukin 15)
Diseases named in the same sentence as IL15 in open-access papers (continued):
Sharing a sentence is not in itself a finding about the gene and the disease.
vitiligo (continued). "Oxidative stress increased IL-15 expression to activate CD8+ T cells by p65 signaling in vitiligo." (PMID 37287971, 2023). "Also, in a mouse model of vitiligo, blocking IL-15 signaling with an antibody reversed the disease symptoms." (PMID 37881433, 2023). "IL-15 expression is increased in vitiligo epidermis, and is induced by oxidative stress via NF-κB." (PMID 37881433, 2023). "Moreover, keratinocytes secrete cytokines and chemokines including CXCL-9, CXCL-10, and IL-15 that amplify the inflammatory circuit within vitiligo skin and recruit melanocyte-specific, skin-resident memory T cells." (PMID 37275386, 2023). "Furthermore, IL-15R, which is essential for IL-15 transpresentation, is increasingly expressed by perilesional keratinocytes in patients with vitiligo." (PMID 35884944, 2022). "Cytokine mediators such as IFN-γ and IL-15 are key cytokine drivers of vitiligo." (PMID 35884944, 2022). "Other labs have mapped additional roles IL-15 plays in vitiligo." (PMID 34012438, 2021). "In response to IL-12, IL-15, and IL-18, they secrete IFNγ; a signature vitiligo cytokine." (PMID 33936032, 2021). "IL-15 expression is elevated in vitiligo lesional skin and may be induced by oxidative stress in keratinocytes." (PMID 33737930, 2021). "Hence, targeting IL-15 signaling with an anti-CD122 antibody has been suggested as a treatment strategy for vitiligo." (PMID 34445713, 2021). "Additionally, in a preclinical mouse model of vitiligo, antibody-mediated inhibition of IL-15 signaling provided long-lasting repigmentation." (PMID 34371735, 2021). "In addition, NK cells receptors, including natural killer cell triggering receptor (NKTR), killer cell lectin-like receptor C1 (KLRC1), CCL20, and NK cell-related cytokines such as TNFα and IL-15, are also increased in perilesional skin in patients with vitiligo." (PMID 35884944, 2022). "Also, targeting IL-15 signaling using an anti-CD122 antibody reversed established vitiligo in mice." (PMID 36154894, 2022). "Therefore, targeting IL-15 may provide a durable treatment option for vitiligo, and clinical trials to test this hypothesis are imminent." (PMID 33737930, 2021). "Together, these findings underscore the pivotal role of IL-15 and its downstream JAK-STAT signaling axis in regulating TRM cell function and maintaining autoimmune responses in vitiligo." (PMID 40791580, 2025). "In vitiligo, The activation of TRM1, which exhibit the expression of effector molecules such as perforin and granzyme B upon stimulation with IL‐15, promotes a robust cytotoxic response, contributing to the pathogenesis of the disease." (PMID 40066223, 2025). "In conclusion, targeting the IL-15/CD122 signaling pathway represents a novel and mechanistically grounded approach to disrupting autoimmune memory in vitiligo." (PMID 40791580, 2025). "In the existence of IL-15, ISG15 significantly induces the excretion of IFN-γ, contributing to the pathogenesis and progression of vitiligo, ultimately leading to melanocyte damage." (PMID 39872521, 2024). "It has been suggested that relapse is due to persistency in the vitiligo skin of CD8+ tissue-resident memory T cells (Trm), which maintenance and function are promoted by IL-15." (PMID 36902341, 2023). "In both active and stable vitiligo, CRP and IL-15 were significantly higher than controls (p < 0.05)." (PMID 37762802, 2023). "In vitiligo mice, an anti-CD122 antibody that targets IL-15 signaling was reported to effectively reverse depigmentation." (PMID 36119071, 2022). "Multiple monoclonal antibodies are available for vitiligo treatment, targeting IFN-γ, CXCL10, CXCR3, HSP70i, IL-15, IL-17/23, and TNF." (PMID 36119071, 2022). "The main cytokine networks explored in the pathogenesis of vitiligo are IFN-γ and TNF-α, in addition to IL-15 and Th17-related cytokines such as IL-17 and IL-23." (PMID 35884944, 2022).
vitiligo (continued). "In vitiligo lesions, CD122 and CD132 are expressed on MSA-specific CD8+ TRM, whereas CD215 is expressed on keratinocytes with an ability to present IL-15 to T cells in trans." (PMID 35432377, 2022). "Thus, targeting IL-15 signaling via CD122 may be a promising therapy for vitiligo." (PMID 33633737, 2020). "The vitiligo case exhibited even higher ISG15 and PRF1, while IFNG, TNF, IL12, and IL15 levels were closer to those in healthy controls." (PMID 33384688, 2020). "In dogs, we found enrichment of T cell gene signatures, with upregulation of IFNG, TNF, PRF1, IL15, CTSW, CXCL10, and CCL5 in both VKH and vitiligo in dogs compared to healthy controls." (PMID 33384688, 2020). "Inhibition of JAK kinases has been shown to disrupt IL-15 signaling, reduce TRM cell activity, and alleviate tissue damage in autoimmune conditions, supporting the therapeutic potential of JAK inhibitors in treating diseases like vitiligo." (PMID 40791580, 2025). "IFN-γ, CXCL9, CXCL10, CXCL11, IL-6, and IL-15 were expressed at higher levels in the circulation of patients with both segmental and non-segmental vitiligo compared to healthy controls (p < 0.001)." (PMID 39981245, 2025). "Additionally, in vitiligo mouse models, an anti-CD122 antibody that targets IL-15 signaling was reported to effectively reverse depigmentation." (PMID 37275386, 2023). "It has been established that IL-15 seems to participate in IL-17 regulation and maintenance of TRM signals, with the latter responsible for long-term maintenance and potential relapse of vitiligo." (PMID 36119071, 2022). "In addition, cytokine, including HSP70i, IL-15, IL-17/23, TNF as well as wnt signaling pathway, Tregs, miRNAs have also been proved to be involved in the pathogenesis of vitiligo." (PMID 36119071, 2022). "Moreover, there is an increase in proinflammatory cytokines, characteristic of innate immunity, in both serum and skin of patients with vitiligo, such as IL1α, IL1β, IL6, IL8, IL12, IL15, and TNFα." (PMID 35643735, 2022). "Research is in progress to investigate the important cytokines involved in the pathogenesis of vitiligo, including IFN-γ, CXCL10, CXCR3, HSP70i, IL-15, IL-17/23, and TNF, the blockade of which has undergone preliminary attempts in animal models and some patients." (PMID 36119071, 2022). "In addition, IL-15 is able to intensify the cytotoxic potential of CD49a+ TRM cells, as well as the production of IFN-γ, the major driver of vitiligo." (PMID 35884944, 2022). "In addition, increased levels of innate immunity cytokines including interleukin (IL)-1α, IL-1β, IL-6, IL-8, IL-12, IL-15 and tumor necrosis factor (TNF)-α have been detected in the sera of patients with vitiligo." (PMID 35884944, 2022). "Our results showed that, except for IL-15, the levels of these factors were significantly higher in recurrent patients compared to persistent stable patients, which suggest that increased levels of IFN-γ, CXCL9, CXCL10, CXCL11 and IL-6 are potential triggers for vitiligo recurrence." (PMID 39981245, 2025). "Furthermore, higher levels of CRP, IL-15, CXCL9, and CXCL10 are identified in active vitiligo." (PMID 37762802, 2023). "Furthermore, the anti-CD122 antibody has demonstrated reverse of the disease in mice, so targeting IL-15 signaling through the anti-CD122 antibody could represent a possible successful and durable treatment for vitiligo." (PMID 36902341, 2023).
Autoimmunity (31 papers, 2007 to 2025). The occurrence of an immune reaction against the organism's own cells or tissues. "There is an intriguing dichotomy in the function of cytokine interleukin-15—at low levels, it is required for the homeostasis of the immune system, yet when it is upregulated in response to pathogenic infections or in autoimmunity, IL-15 drives inflammation." (PMID 38405398, 2024). "Owing to its clear involvement in these pathologies, a series of IL-15-directed antagonistic approaches have been developed to limit aberrant immune stimulation and decrease the risk of autoimmunity related to uncontrolled IL-15 exposure." (PMID 35592318, 2022). "Furthermore, the systemic administration of IL15 carries the risk of potential toxic side effects, including the induction of autoimmunity." (PMID 35758207, 2022). "For example, elevated IL-15 signaling relative to baseline has been associated with pathogenesis of autoimmune disorders, so in that context, it may be beneficial to inhibit IL-15 signaling." (PMID 34578331, 2021). "On the other hand, this increased polyclonal T cell responsiveness could lead to increased risks of autoimmunity or immune-mediated inflammatory disease as adverse effects associated with IL-15 adjuvanted vaccinations or immunotherapies." (PMID 21408124, 2011). "However, given the already elevated cytotoxic potential and pro-inflammatory profile in elderly females, systemic IL-2 or IL-15 administration could carry risks, such as immune overstimulation or increased susceptibility to autoimmunity." (PMID 41194200, 2025). "Thus, IL-15/IL-15Rα activates the JAK1/JAK3 and STAT3/STAT5 pathways to induce proliferation of T and NK cells, and this mechanism could limit exposure to circulating IL-15, that contributeS to the risk of autoimmunity." (PMID 22888423, 2012). "However, all three of IL-2, IL-15 and IL-21 have been implicated in autoimmunity, and using such cytokines to activate endogenous NK cells may favour inflammation and promote autoreactivity." (PMID 18053164, 2007). "Nonetheless, there have been recent efforts focused on targeting memory T cells in recurrence autoimmunity, with strategies such as blocking IL-7 and IL-15 signaling showing promise in reversing new-onset autoimmune diabetes in NOD mice." (PMID 40182604, 2025). "As chronic over-expression of IL-15 can lead to autoimmunity, IL-15 expression is tightly regulated." (PMID 38405398, 2024). "Here, we discuss the regulation of IL-15 expression and delineate the homeostatic and proinflammatory signalling of IL-15 in lymphocytes and their role in driving the pathogenesis of several autoimmune conditions." (PMID 38405398, 2024). "Further, while IL-2 promotes activation-induced cell death and tolerance in many of these cell types, IL-15 is known to prolong the survival of cytotoxic lineages and promote autoimmunity." (PMID 38405398, 2024). "IL-15 induces the synthesis of certain cytokines that participate in autoimmunity like, for example, TNF-α and IL-1β, by enhancing the maintenance of CD-8 memory T-cell through the inhibition of self-tolerance." (PMID 37206670, 2023). "This immunological synapse is thought to limit exposure to circulating IL-15, in which uncontrolled expression would undeniably lead to the induction of autoimmunity." (PMID 35592318, 2022). "Interleukin-15 (IL-15) is a proinflammatory cytokine expressed by a broad range of tissues and contributes to chronic inflammation and autoimmunity." (PMID 35747794, 2022). "IL-15 protein expression is heavily regulated by multiple negative feedback loops to prevent aberrant immune activation and autoimmunity." (PMID 34578331, 2021). "We have previously noted that localized tissue expression of MICA and IL-15 can lead to autoimmunity mediated by CD8+ effector T cells, likely due to the capability of IL-15 to drive the expression of NKG2D and activate its cytolytic pathway." (PMID 24086722, 2013).
Autoimmunity (continued). "Some studies speculate that the collapse of immune privilege in hair follicles caused by IFN-γ produced by CD8+ T cells induces the production of IL-15 and promotes type I cell autoimmunity, thereby facilitating the onset of AA." (PMID 40292287, 2025). "In vitro IL‐2 and IL‐15 activities are indissociable when purified CD8+ T cells are used; however, IL‐2 deficiency is associated with lymphoproliferative disorders and autoimmunity." (PMID 36705415, 2023). "The importance of autoimmunity and genetics in the disease’s development is demonstrated by the presence of several preclinical studies involving IL-15 pathways; studies targeting the production of ROS, DAMPs, and antioxidant pathways or chemokine receptors; and stimulating melanocyte stem cells." (PMID 36902341, 2023). "Results indicated that IL-2/IL-15 and IL-2/IL-21 pretreated groups showed significant autoimmunity against MSCs, which are consistent to the expression of activating receptors and intracellular levels of cytotoxic soluble factors (Supplementary 4) in the NK cell culture." (PMID 38106519, 2023). "The serum levels of pro-inflammatory and immunomodulatory cytokines such as IL-1β, IL-6, IL-8, IL-10, IL-17, and IL-15 were used as secondary study endpoints as they provide a strong evidence of the efficacy of the hMSCs administration inmodulating autoimmunity." (PMID 30254638, 2018). "It is attractive to speculate that IL-15-induced STAT3 activation may serve to counteract the IL-15-STAT5-mediated NK-cell cytotoxicity to prevent autoimmunity." (PMID 28149296, 2016). "Our study points to a potential role for NK cells in autoimmune disorders where specific tissue cell types would be destroyed based not on the recognition of self-antigens by T cells but instead on the expression of IL-15 and stress ligands, stimulating activating NK receptors such as NKG2D." (PMID 24086722, 2013). "Ex vivo culture of NK cells with cytokines such as IL-2 and IL-15 is an approach that permits significant expansion of the NK cell subpopulations, which are likely to have potent antitumour, antiviral, or immunomodulatory effects in autoimmunity." (PMID 18053164, 2007). "Under physiologic conditions the activities of IL15 are tightly regulated, however it is evident that in pathologic settings dysregulated IL15 may be either disadvantageous as is the case in autoimmunity, or beneficial in boosting the immune response to cancer." (PMID 26822794, 2016). "Our data are in agreement with above reported studies and suggest that the increase of IL-15 in TET-AD patients might sustain T cell enhanced population and autoimmunity." (PMID 36059463, 2022). "Conceivably, innate immune danger signals, such IL-15, serve to boost the protective responses to pathogens that are otherwise faintly stimulatory to CD4+ T cells, while preventing unwanted systemic stimulation of unrelated CD4+ T cells and thus autoimmunity." (PMID 23028916, 2012). "Finally, NKG2D, a powerful activating receptor involved in the regulation of immune responses during infection, cancer and autoimmunity, was preferentially detected on CD34-lineage- cells cultured with IL-15 and IL-21." (PMID 19712464, 2009). "In the current study, IL-2 and IL-15 stimulation was identified to preferentially shift NK cell from NK0 (inactivated status) to a dominant NK1 phenotype, which could potentially lead to long-term inflammation and development of autoimmunity in the culture." (PMID 38106519, 2023). "IL-21 affects the differentiation and proliferation of NK cells together with IL-2 and IL-15, and is involved in the differentiation of T-helper 17 (Th17) cells, a recently identified subset of CD4+ T cells that produce IL-17A, IL-17F and IL-22 and promote inflammatory and autoimmune conditions." (PMID 19712464, 2009).
colorectal cancer (31 papers, 2016 to 2025). A primary or metastatic malignant neoplasm that affects the colon or rectum. "High IL-15 expression is linked to a decreased recurrence in patients with colorectal cancer, and an increased level of plasma IL-15 was associated with clinical benefit of checkpoint inhibitors in lung cancer patients." (PMID 36831406, 2023). "IL-15 can also regulate the growth and apoptosis of colorectal cancer tumor cells, and low level of IL-15 is also associated with low-infiltrating lymphocytes in tumor microenvironment and poor prognosis of the colorectal cancer." (PMID 36969190, 2023). "Genomic abnormalities targeting cytokines and cytokine receptors clusters are described in several types of tumors, such as loss of chromosome 4 and the subsequent decreased IL15 expression in colorectal cancer." (PMID 29515972, 2018). "For example, a study involving 116 patients with stage I–III breast and colorectal cancer, randomized to 12 weeks of either aerobic exercise or metformin pharmacotherapy, demonstrated dichotomic effects on IL-15." (PMID 40642656, 2025). "To clarify the mechanistic relevance of IL-7 and IL-15 in colorectal cancer, we conducted a secondary analysis of the Exercise and Colorectal Cancer Treatment (EXACT) trial." (PMID 40642656, 2025). "Despite these limitations, the approach to investigating both IL-7 and IL-15 provides valuable insights into the effects of exercise on immune-related exerkines in colorectal cancer survivors." (PMID 40642656, 2025). "The plasma levels of several cytokines (interleukin-1β /IL-1β/, IL-2, IL-4, IL-10, IL-12, IL-15, TGFβ and IFNγ) of 20 patients with colorectal cancer and 21 healthy individuals were determined by ELISA." (PMID 39456247, 2024). "A fusion protein called RLI, composed of the sushi domain of IL-15 receptor α coupled via a linker to IL-15, seems to have a high antitumor activity in metastatic melanoma and colorectal cancer in mice." (PMID 31996218, 2020). "Given its role in the development of NK and cytotoxic T cells, IL-15 has been identified as an anti-tumor cytokine in models for breast and colorectal cancer." (PMID 28379958, 2017). "Given its ability to attract CD8+ T cells and NK cells towards the tumor site, IL-15 has been identified as an anti-tumor cytokine in several models, including: neuroblastoma, breast and colorectal cancer." (PMID 28379958, 2017). "AM0010, a recombinant human interleukin 10 (IL-10), interleukin 15 (IL-15) and interleukin 12 (IL-12) are recently used in colorectal cancer studies." (PMID 27974927, 2016). "Therefore, it is possible that the mechanism of suppressing colorectal cancers by FMT in this model was tumor suppression by increased IL-15 expression due to an increased abundance of Lactobacillaceae." (PMID 40431182, 2025). "This study investigated whether a 12-week structured exercise training intervention increases IL-7 and IL-15 in colorectal cancer survivors." (PMID 40642656, 2025). "Aerobic exercise may improve immune function in colorectal cancer survivors by restoring IL-7 after chemotherapy and improving IL-15 by altering body composition." (PMID 40642656, 2025). "We hypothesized that 12 weeks of moderate-intensity aerobic exercise compared with a control condition would restore circulating IL-7 and IL-15 in colorectal cancer survivors in a pattern compatible with an improved cancer prognosis." (PMID 40642656, 2025). "Interestingly, recent literature data, obtained in solid tumors including colorectal carcinoma, have suggested that both IL-15/IL-15α axis and TGF-β/SMAD-3 pathway are also involved in determining the effectiveness of the anti-EGFR agent, cetuximab." (PMID 33916844, 2021). "Based on these data and the correlations with cytokine levels, it can be concluded that CD25, CD80, CD86, CD274 and CD279 glycoproteins combined with specific plasma levels of IL-1β, IL-2, IL-15 and TGFβ could represent potential biomarkers for colorectal cancer." (PMID 39456247, 2024).